TLR4 (toll like receptor 4)
Diseases named in the same sentence as TLR4 in open-access papers (continued):
Sharing a sentence is not in itself a finding about the gene and the disease.
Insulin resistance (continued). "Insulin resistance associated with absent TLR2 signaling may be attributed to increased serum lipopolysaccharide (LPS) activation of toll-like receptor 4 (TLR4) in the muscle, liver, and adipose tissue." (PMID 31182162, 2019). "Activation of TLR4 by saturated fatty acids elicits, through the activation of NFκB, the secretion of several proinflammatory cytokines such as TNF-α, IL-6, and MCP-1, which are involved in the development of obesity-associated inflammation and insulin resistance." (PMID 30116154, 2018). "Thus, gliadin may induce insulin resistance and beta-cell dysfunction through TLR4 and possibly also through other innate immune receptors." (PMID 30428550, 2018). "The increases in monocyte TLR4 and phosphorylated JNK and p38 levels caused by lipid infusion were associated with enhanced production of multiple cytokines, including IL-1β, IL-6, MCP-1, and TNFα, all of which have been implicated in insulin resistance and type 2 diabetes." (PMID 29649324, 2018). "Upon binding to the complex of CD14 and toll-like receptor 4 at the surface of innate immune cells, LPS can trigger the secretion of proinflammatory cytokines, which eventually impairs insulin sensitivity and induces insulin resistance-related metabolic disorders." (PMID 27036035, 2016). "Furthermore, TLR4/CD14 signaling can induce hepatic insulin resistance." (PMID 26751951, 2016). "Because of a pathophysiologic role for FFA-induced TLR4 activation in inflammation and insulin resistance, it is hypothesized that GHP, the inhibitor for bacterial LPS-induced inflammatory response, may contribute to the control of endogenous lipid-induced insulin resistance." (PMID 25923657, 2015). "Moreover, deletion of TLR2 or TLR4 in rodents attenuates atherosclerosis and insulin resistance." (PMID 23671849, 2013). "Consequently, we may not rule out an implication of intracellular lipids in the link between TLR4 dependent-ER stress and insulin resistance." (PMID 23741455, 2013). "The physiologic relevance of the increased TLR4 protein content is underscored by studies in which TLR4 was ablated specifically in hematopoietic cells from mice, an intervention which reduced inflammatory markers in liver and adipose tissue and ameliorated high-fat diet-induced insulin resistance." (PMID 23671849, 2013). "Overall, these results suggest that the overexpression of TLR2 and TLR4 on both PBMCs and adipose tissues together with the enhanced production of proinflammatory cytokines may pave way for the development of insulin resistance in obese individuals, leading to type 2 diabetes." (PMID 23191980, 2012). "TLR4 is expressed on Kupffer cells and other liver cell components and modulates liver pro-inflammatory activity induced by high-fat diet- and fructose-induced hepatic steatosis and insulin resistance in mouse models, although a direct role for liver tissue TLR4 in these processes is unclear." (PMID 20814545, 2010). "Finally, recent work has shown clearly that TLR4 could also be activated, not only by LPS, but also by lipids in food, especially saturated ones, thus explaining the development of insulin resistance." (PMID 20148136, 2010). "Stearoyl CoA desaturase 1 (SCD1) deficient mice, although protected from high-fat diet-induced insulin resistance, accumulate macrophage plasma membrane SFA, exhibit greater susceptibility to atherosclerosis, and are hypersensitive to inflammatory stimuli including those signaling through TLR4." (PMID 20814545, 2010). "In summary, there is evidence that TLR4 may provide the molecular mechanism that links increased SFFAs in obese subjects to the observed chronic low-grade inflammatory state and subsequent manifestation of insulin resistance." (PMID 21125016, 2010).
Insulin resistance (continued). "NF-κB and JNK represent important modulators of inflammatory gene expression downstream of TLR4 in adipose tissues, suggesting that food components interfering with the TLR4/NF-κB or TLR4/JNK axis could be useful to prevent the onset of insulin resistance in obese patients." (PMID 20508825, 2010). "Interestingly, acute LPS treatment inhibits hepatic glucose production in vivo and in vitro via a TLR4 signaling pathway and induces insulin resistance 48 hours post-treatment in vivo, suggesting possible cross-talk between TLR4 and insulin receptor signaling pathways in this system." (PMID 20814545, 2010). "Results: miR-122 was found to negatively regulate genes involved in lipid metabolism, insulin signaling, and inflammatory pathways, including PPARGC1A, PPARA, LPL, TLR4, and HMGCR, contributing to insulin resistance and liver dysfunction." (PMID 41595656, 2026). "It has been shown that sEVs derived from adipose tissue of obese mice induce insulin resistance in healthy mice, through mechanisms involving TNF-α and Toll like receptor-4 (TLR4)." (PMID 39422717, 2025). "LPS triggers Toll-like receptor 4 (TLR4) activation, leading to NF-κB pathway stimulation and increased pro-inflammatory cytokine production, contributing to insulin resistance." (PMID 40308637, 2025). "In rats consuming a high fructose diet, hepatic activation of TLR4, NLRP3, NFκB, and JNK with the inhibition of AMPK leads to inflammation and insulin resistance." (PMID 40725208, 2025). "This process activates Toll-like receptor 4 (TLR4) signaling, contributing to insulin resistance in adipose and hepatic tissues." (PMID 41220415, 2025). "This condition exacerbates metabolic disruptions by activating Toll-like receptor 4 (TLR4) on macrophages, leading to the release of pro-inflammatory cytokines and subsequent insulin resistance." (PMID 40530326, 2025). "Increased plasma LPS promotes the activation of Toll-like receptor 4 (TLR4) signaling in adipose tissue and hepatocytes, leading to elevated NF-κB-mediated inflammation and insulin resistance." (PMID 41471280, 2025). "Studies in mice have shown that HFD feeding upregulates TLR4 expression in pancreatic islet macrophages, whereas TLR4 knockout abrogates FFA-induced IL-1β secretion and insulin resistance." (PMID 41321403, 2025). "LPS activates Toll-like receptor 4 (TLR4) and the NF-κB inflammatory cascade, inducing a chronic low-grade inflammatory state that promotes insulin resistance and fat accumulation." (PMID 40725626, 2025). "Its documented suppression of the TLR4/NF-κB and NLRP3/caspase-1 axes directly counteracts the chronic low-grade inflammation that underpins insulin resistance." (PMID 41459066, 2025). "Further, flavonoid-based dietary interventions alleviated inflammation as measured through LPS/TLR-4, TNF-α, IL-6, and IL-10, while also improving insulin resistance, HgbA1c, and oral glucose tolerance." (PMID 38257161, 2024). "This reduction in LPS-driven inflammation is important, as LPS is known to activate Toll-like receptor 4 (TLR4), which triggers pro-inflammatory signaling pathways and insulin resistance." (PMID 39502877, 2024). "Moreover, synbiotics have been reported to improve gut integrity via SCFA production, by which inhibiting the TLR4–LPS complex-triggered proinflammatory cascade, hampering proinflammatory cytokine signaling pathways, such as nuclear factor kappa B (NF-κB), thereby decreasing insulin resistance." (PMID 37929031, 2023). "HMGB1 accelerates insulin resistance by increasing the expression of RAGE, activating the TLR4/JNK/NF-κB pathway and reducing activation of the IRS-1 signaling pathway." (PMID 37065747, 2023). "In instances of insulin resistance, RBP4 can trigger pro-inflammatory cytokine activation in macrophages via the c-Jun N-terminal protein kinase and TLR4 pathways." (PMID 38155961, 2023).
Insulin resistance (continued). "Salidroside is the primary active ingredient of Rhodiola and can alleviate insulin resistance, hyperglycemia, and liver inflammation in db/db mice by inhibiting the HMGB1/RAGE/NF-κB and HMGB1/TLR4/NLRP3 signaling pathways." (PMID 37065747, 2023). "By contrast, in the later stages of liver disease, the activation of Toll-like receptor 4 (TLR4) by lipopolysaccharide induces inflammation, ceramide biosynthesis, and insulin resistance." (PMID 37223039, 2023). "During obesity, de novo ceramide synthesis increases during inflammation and insulin resistance due to an influx of FFA increasing a ceramide precursor, palmitoyl CoA, and by activating TLR4 on immune cells." (PMID 37764683, 2023). "Specifically, the reduced ARC inflammation by ARC-restricted TLR4 knockdown protects HFD-fed animals from impaired glucose homeostasis and peripheral insulin resistance." (PMID 35628338, 2022). "• T cell activation. • Induction of inflammatory molecules like IL8, IL12A, CCL5, CCL19, CCR2, and CCR5. • Contribution to increased insulin resistance secondary to TLR2, TLR4, and TLR10 interaction." (PMID 35422689, 2022). "In summary, genetic inactivation of Tlr4 in TLR2−/− mice reverts their increased adiposity and insulin resistance." (PMID 36555322, 2022). "A study showed that BBR set-back these effects and restrained LPS-induced TLR4/TNF-α activation, leading to increased insulin receptor and insulin receptor substrate-1 expression in the liver and reduce insulin resistance." (PMID 36093200, 2022). "Interestingly, HFD directly stimulates TLR4/ NF-κB signaling, leading to increased local inflammation through upregulation of TNF-α, which may contribute to low-grade systemic inflammation associated with insulin resistance." (PMID 36329549, 2022). "RBP4 can act through toll-like receptor 4 (TLR4) and activate the c-Jun N-terminal protein kinase (JNK) pathway, improving insulin resistance." (PMID 35887234, 2022). "FFA-induced Fetuin-A functions as an endogenous ligand of Toll-like receptor 4 (TLR4), and exacerbates lipid-mediated insulin resistance." (PMID 33925827, 2021). "CCN4 can also activate the TLR4/JNK signaling pathway, linking CCN4-induced insulin resistance with inflammation." (PMID 33946738, 2021). "Fetuin-A also acted as an endogenous ligand for Toll-like receptor 4 (TLR4), which contributes to the free fatty acid (FFA)-induced insulin resistance in adipocytes, macrophage invasion, and inflammation." (PMID 33498410, 2021). "Through modulating TLR4 signaling, SAA reduces oxidative stress, inflammation, and apoptosis in liver tissue during insulin resistance." (PMID 33762947, 2021). "High glucose facilitates the expression of TLR4 and then the activation of TLR4 mediates oxidative stress, aggravating the HRMEC dysfunction and insulin resistance." (PMID 34692851, 2021). "Mechanism research reveals that NK-derived exosomal miR-1249-3p relieves insulin resistance and inflammation by targeting SKOR1, which interacts with SMAD6 and promotes glucose homeostasis by suppressing the TLR4/NF-κB signaling pathway." (PMID 34848693, 2021). "Fetuin-A augments adipose tissue inflammation via activation of toll-like receptor 4 (TLR4), thereby being a major determinant of insulin resistance and type 2 diabetes." (PMID 33765181, 2021). "TLR4 signal leads to the production of proinflammatory cytokines in the target tissue of HFD mice and leads to chronic inflammation and insulin resistance." (PMID 33551809, 2020). "A recent study showed that TLR4 signaling mediates inflammatory responses in adipose tissue and skeletal muscle leading to HFD-induced insulin resistance." (PMID 32097444, 2020). "Withaferin A decreases the gene expression of TLR4 and COX-2, which protects high-fat diet-induced mice against metabolic disorders such as glucose tolerance, insulin resistance, and oxidative stress." (PMID 33291425, 2020).
Insulin resistance (continued). "The interaction between ox-LDL and Toll-like receptor 4 (TLR4) activates NF-κB path way resulting in elevated expression of pro-inflammatory cytokines including IL-1β, IL-6, and TNF-α which induce insulin resistance." (PMID 32005271, 2020). "For insulin resistance, β-cell dysfunction by saturated fat was prevented in TLR2- and TLR4-null mice, and in NLRP3-null mice." (PMID 32183037, 2020). "Previous studies found that the TLR-4-LPS pathway can stimulate pro-inflammatory cytokines in the skeletal muscle, and pro-inflammatory cytokines, such as TNF-α, promote insulin resistance though NF-kB inflammatory signaling." (PMID 33019697, 2020). "In addition, the beneficial effects of the oil mixture treatment on aging-induced endothelial dysfunction could also be the result of decrease % of SFA, since SFA are reported to mediate vascular endothelial inflammation and insulin resistance through TLR4-mediated NF-κB and MAPK pathways." (PMID 32503213, 2020). "Our results indicate that high-glucose load leads to glucose intolerance with insulin resistance through impairment of GLP-1 secretion, increase of blood glucose levels via activating TLR4 and increasing levels of IL-6 and TNF-α in mice." (PMID 31138952, 2019). "We revealed that FBXW7 effectively abated the expression and release of HMGB1, thereby suppressing TLR4 and RAGE signaling to attenuate inflammation and consequent insulin resistance, ultimately ameliorating NAFLD." (PMID 31215394, 2019). "Muscle TLR4 protein content correlates with body fat percentage in older adults and is related to NEFA-induced insulin resistance." (PMID 31263701, 2019). "In an acute experiment, rats that received a TLR4 inhibitor (TAK-242 or E5564) obtain partial protection against acute and chronic fat-induced insulin resistance." (PMID 31582899, 2019). "This ultimately leads to insulin resistance especially in the continuous or chronic and persistent stimulation of the TLR signaling pathway through expression of TLR4, MyD88 and NFκB." (PMID 31738794, 2019). "Fructose metabolism in hepatocytes is associated with increased XO-mediated conversion of AMP to uric acid, which promotes insulin resistance through RAGE, TLR4, NF-κB, Nox, mitochondrial oxidative stress, ER stress, and skeletal muscle atrophy." (PMID 30116482, 2018). "Activation and signaling of Toll-like receptor 4 (TLR4) by FFAs induces inflammation evident in NAFLD and insulin resistance." (PMID 29666152, 2018). "Furthermore, lipid-induced increases in TLR4 and p38 phosphorylation directly correlated with reduced M value, further suggesting that TLR4 signaling in monocytes could play a role in lipid-induced insulin resistance in humans." (PMID 29649324, 2018). "Loss of TLR4 function partially restored a healthy metabolic phenotype, suggesting that TLR4 signaling is a key mechanism in HFD-induced peripheral and cardiac insulin resistance." (PMID 26539824, 2015). "Using two well-established models of fat-induced insulin resistance (acute lipid infusion and chronic HFD administration), we evaluated the effects of pharmacological TLR4 inhibition on peripheral and hepatic insulin action." (PMID 26196892, 2015). "It is well known that free fatty acids (FFAs) stimulate secretion of proinflammatory cytokines from adipocytes through Toll-like receptor 4 (TLR4), resulting in insulin resistance." (PMID 24551137, 2014). "Recently, a liver secretory glycoprotein, fetuin-A, was demonstrated to play a crucial role as an endogenous ligand for TLR4 in FFA-induced inflammation and insulin resistance in adipocytes." (PMID 23964268, 2013). "Therefore, TLR4 could be the missing link between high circulating lipids and insulin resistance." (PMID 23741455, 2013).
Insulin resistance (continued). "Fetuin-A, a liver secretory glycoprotein with 64 kDa, has been shown that it acts as carrier of free fatty acids (FFAs) and they are the intrinsic ligands for Toll-like receptor 4 (TLR4), which induces adipose tissue inflammation and insulin resistance." (PMID 24143207, 2013). "In particular, TLR4 and TLR9 agonists induced inflammation and insulin resistance; this feature is transmissible to newborn and adult mice that come in direct contact with inflammasome-deficient animals." (PMID 23840101, 2013). "Another study demonstrated that fetuin-A acted as an endogenous ligand of TLR4, played a key role in FFA-induced proinflammatory cytokine expression, and promoted lipid-induced insulin resistance." (PMID 23710462, 2013). "Saturated free fatty acid and gut-derived bacterial lipopolysaccharide (LPS) also bind to Toll-like receptor 4 (TLR4) to activate NF-κB and JNK and mediate inflammation and insulin resistance." (PMID 23781214, 2013). "Insulin resistance, as measured by HOMA-IR was significantly higher in TLR4 mutant mice compared to WT mice when received TF diet (11.2 vs. 1.77; P < 0.001)." (PMID 21314942, 2011). "Toll-Like Receptor 4 (TLR4), involved in modulating innate immunity, is an important mediator of insulin resistance and its comorbidities." (PMID 20814545, 2010). "Among them, LPS binds to TLR4 on the surface of hepatocytes and activates Kupffer cells to release pro-inflammatory factors (IL-6, TNF-α), which further inhibits insulin receptor substrate (IRS) phosphorylation and exacerbates intrahepatic insulin resistance." (PMID 41048505, 2025). "These processes converge on signaling pathways such as Toll-like receptor 4/nuclear factor-κB, c-Jun n-terminal kinase, and the NOD-like receptor family pyrin domain-containing protein 3 (NLRP3) inflammasome, leading to insulin resistance, endothelial dysfunction, and atherogenesis." (PMID 41301434, 2025). "LPS from the outer membrane of gram‐negative bacteria bind to toll‐like receptor 4 (TLR4), triggering the release of pro‐inflammatory cytokines and leading to insulin resistance." (PMID 40525652, 2025). "Elevated levels of HMGB1 and its receptors, RAGE and TLR4 proteins, were found in the lung tissue of smoking COPD patients, and CS-induced HMGB1 secretion may lead to insulin resistance." (PMID 40216765, 2025). "Blocking TLR4 can improve the insulin-dependent intake of glucose and alleviate insulin resistance induced by HFD in mice, which may be because the knockout of TLR4 leads to a decrease in inflammatory factors." (PMID 38275739, 2024). "When insulin resistance is present, the expression of proteins named high-mobility group box-1 (HMGB1) and receptor for advanced glycation end-products (RAGE) is elevated, resulting in the subsequent activation of toll-like receptor 4 (TLR4)." (PMID 37511207, 2023). "It was evidenced that mice lacking CD14, a co-receptor of TLR-4, were more hyperinsulinemia-resistant and insulin resistance induced by a high-fat diet or LPS." (PMID 37009872, 2023). "The regulation of the TLR4 pathway by DOP treatment has been reported in vitro; however, the mechanism on the regulation of the TLR4 signal pathway by DOP to improve insulin resistance was not documented." (PMID 37372523, 2023). "This inflammatory state is mediated through toll-like receptor 4 (TLR4) and CD14 in hematopoietic cells, culminating in weight gain, increased adiposity, elevated inflammatory markers in white adipose tissue (WAT) macrophages, and insulin resistance." (PMID 38132864, 2023). "Insulin resistance, elicited by the binding of agonists to tumour necrosis factor receptor superfamily member 1A (TNFR1) and toll-like receptor 4 (TLR4), activate the JAK signalling pathway that phosphorylates serine at insulin receptor substrates 1 and 2 (IRS1, 2)." (PMID 35328666, 2022).